EGF (epidermal growth factor)
Diseases named in the same sentence as EGF in open-access papers (continued):
Sharing a sentence is not in itself a finding about the gene and the disease.
colon carcinoma (continued). "In the present study, changes of integrin β1 expression and localization were examined in HCT116 colon cancer cells after EGF exposure." (PMID 29515334, 2018). "Specifically, total integrin β1 protein levels were markedly lower in HCT116 colon cancer cells treated with EGF for 24 h." (PMID 29515334, 2018). "HCT116 human colon cancer cells were treated with increasing concentrations of EGF, and cell proliferation and protein expression were monitored by MTT and western blot analyses, respectively." (PMID 29515334, 2018). "Among extracellular signals pathways over-represented in differentiated Caco-2 cells most of them are well described in the process of colon cancer, such as Notch, extracellular matrix, Wnt, or EGF, which is involved in differentiation." (PMID 28726765, 2017). "Recently, EGF stimulation was shown to increase HO-1 through NF-kβ activation in colon cancer and in non-small cell lung cancer." (PMID 28500562, 2017). "We constructed a model of the signalling network downstream of TNF α and EGF in HT-29 human colon carcinoma cells, formalizing the crosstalk that takes place between the pathways at different levels of cellular regulation." (PMID 27460034, 2016). "We show this by presenting ANIMO models for two case studies: Drosophila melanogaster circadian clock, and signal transduction events downstream of TNF α and EGF in HT-29 human colon carcinoma cells." (PMID 27460034, 2016). "We also showed the construction of an executable model of signalling events downstream of TNF α and EGF in human colon carcinoma cells." (PMID 27460034, 2016). "In contrast, maraviroc reduced the intratumor number of α-smooth muscle actin-positive fibroblasts, which express epidermal growth factor, a crucial growth factor for colon cancer cell growth." (PMID 27340784, 2016). "In line with our observation, EGF was demonstrated to induce morphological changes in colon cancer cell lines whereas AREG had an effect only on cell proliferation." (PMID 27643613, 2016). "The results above showed that the inhibition of EGF-induced neoplastic cell transformation and colony formation of colon cancer cells by FeF involves the suppression of TOPK kinase activity and, subsequently, TOPK downstream signaling pathways." (PMID 26936995, 2016). "Previous studies have also shown that rapamycin inhibits the basal and epidermal growth factor (EGF) stimulated cell adhesion in colon cancer cells (HCT116)." (PMID 25762619, 2015). "Studies have shown that rapamycin inhibits the basal and epidermal growth factor (EGF) stimulated cell adhesion in colon cancer cells (HCT116)." (PMID 25762619, 2015). "The invasiveness and metastasis functions of KITENIN were shown to be mediated by ERK/AP-1 activation through the interaction of KITENIN with Dvl/PKCδ or the KITENIN/ErbB4-Dvl2-c-Jun axis, as an EGFR-independent EGF signal in colon cancer cells." (PMID 25605251, 2015). "In this study, we present data that confirmed the role of c-Src and NADPH oxidase in EGF-induced NF-κB activation in human colon cancer cells." (PMID 25122478, 2014). "In this study, we investigated the involvement of the c-Src, NADPH oxidase, reactive oxygen species (ROS), PI3K/Akt, and NF-κB signaling pathways in EGF-induced HO-1 expression in human HT-29 colon cancer cells." (PMID 25122478, 2014). "In the present study, we investigated the effects of EGF-induced HO-1 expression in human HT-29 colon cancer cells." (PMID 25122478, 2014). "In the current study, we present data to support the role of the PI3K/Akt signaling pathway in EGF-induced HO-1 expression in human colon cancer cells." (PMID 25122478, 2014). "In this study, we further demonstrated the roles of NADPH oxidase and ROS in EGF-induced HO-1 expression in human colon cancer cells." (PMID 25122478, 2014). "Human HT-29 colon cancer cells were chosen to investigate the signal pathways of EGF in HO-1 expression." (PMID 25122478, 2014).
colon carcinoma (continued). "Results of the present study showed that NF-κB activation is essential for HO-1 expression stimulated by EGF in human colon cancer cells." (PMID 25122478, 2014). "B4GALNT3 knockdown suppresses EGF-induced sphere formation, migration and invasion of colon cancer cells." (PMID 25003232, 2014). "A previous report by Brunton etal. showed that EGF-induced c-Src activation is required for progression of human colon cancer cells." (PMID 25122478, 2014). "In this study, we found that the EGF induced an increase in colon cancer cell proliferation, which was inhibited by snPP (an HO-1 inhibitor)." (PMID 25122478, 2014). "Taken together, these results suggest that activation of c-Src, NADPH oxidase, PI3K, and Akt is required for EGF-induced NF-κB activation in HT-29 human colon cancer cells." (PMID 25122478, 2014). "Taken together, these results suggest that NF-κB activation is necessary for HO-1 expression by EGF in human colon cancer cells." (PMID 25122478, 2014). "An in vitro experiment showed that the CDX2 gene is associated with the increase in sLex/a expression and suppression of FUT2 in colon cancer cells during EGF/bFGF-induced epithelial–mesenchymal transition (EMT)." (PMID 24941225, 2014). "We reported that berberine significantly inhibited basal level and EGF-stimulated EGFR activation and proliferation in the immorto Min mouse colonic epithelial (IMCE) cells carrying the APCmin mutation and human colonic carcinoma cell line, HT-29 cells." (PMID 23457600, 2013). "We next evaluated the effect of Casodex and S1 peptide on DNA synthesis and motility induced by EGF in human colon cancer-derived HCT116 cells." (PMID 24130806, 2013). "In colon cancer cells (HT-29), EGF-induced PI-3K/STAT3 signaling was suggested as an essential pathway regulating VEGF and leptin expression." (PMID 24202338, 2013). "Suppression of EGFR expression and inhibition of receptor tyrosine phosphorylation of EGFR interrupts EGF signaling, which collectively contributes to the inhibition of colon cancer cell growth by curcumin." (PMID 23251236, 2013). "In these EGF-responsive colon cancer cells, EGF induced STAT3 binding to VEGF and leptin promoters and stimulated leptin and VEGF mRNA and protein synthesis." (PMID 24202338, 2013). "We have recently reported that Rho-kinase/ROCK negatively regulates EGF-stimulated colon cancer cell proliferation." (PMID 21722395, 2011). "Active FOXO3 negatively regulates proliferation of colon cancer cells, and we showed that its inactivation is an essential step in EGF-mediated proliferation." (PMID 21639915, 2011). "Active FOXO3 attenuates proliferation by upregulation of the cell cycle inhibitor p27kip1, and we showed that EGF-induced FOXO3 disassociation from the p27kip1 promoter is inhibited by genistein in colon cancer cells." (PMID 21639915, 2011). "Anti-proliferative properties of genistein, exerted by targeting different kinases of various proliferative pathways were assessed on EGF-induced proliferation in colon cancer cells." (PMID 21639915, 2011). "We demonstrated that one of the anti-proliferative mechanisms of genistein in colon cancer cells is to promote FOXO3 activity by inhibiting EGF-induced FOXO3 phosphorylation (inactivation) via the PI3K/Akt pathway." (PMID 21639915, 2011). "We have previously reported that Rho-kinase/ROCK negatively regulates epidermal growth factor (EGF)-induced cell proliferation in SW480 colon cancer cells." (PMID 21722395, 2011). "In this paper we apply a fuzzylogic framework to the analysis of a large, systematic dataset describing thedynamics of cell signaling downstream of TNF, EGF, and insulin receptors inhuman colon carcinoma cells." (PMID 19343194, 2009).
colon carcinoma (continued). "This is the first study to have systematically investigated the effect of cetuximab or gefitinib, alone and in combination with EGF, on human colon cancer cell lines." (PMID 18691415, 2008). "We characterized HT-29 and Caco-2, human colon cancer cell lines, untreated and treated with cetuximab or gefitinib alone and in combination with EGF." (PMID 18691415, 2008). "Tumour growth factor-alpha and epidermal growth factor (EGF) are involved in upregulation of gastrin expression in a number of colon cancer cell lines through binding to an established EGF response element, gERE, within the gastrin promoter." (PMID 17262081, 2007). "Sulindac sulfide and indomethacin inhibit TGFα induced prostaglandin production and thymidine incorporation in RIE-1 cells, and indomethacin, ibuprofen, and aspirin all block EGF-induced Ca++ influx in Caco-2 colon cancer cells." (PMID 16138927, 2005). "HT29 human colon cancer cells were treated with EGF, alone, or in the presence of sulindac sulfide or sulindac sulfone." (PMID 16138927, 2005). "In this regard, c-Src co-operates with migratory growth factors, including epidermal growth factor (EGF), both to induce epithelial cell migration, as well as to induce hepatocyte growth factor (HGF)- or EGF-induced invasion of colon cancer cells in vitro." (PMID 12402152, 2002). "Vascular endothelial growth factor (VEGF) and epidermal growth factor (EGF) regulate colon cancer growth and metastasis." (PMID 11506500, 2001). "We previously reported that exposure of DiFi human colon cancer cells to the anti-epidermal growth factor (EGF) receptor monoclonal antibody (mAb) 225 resulted in apoptosis, but the mechanisms remain to be elucidated." (PMID 10864208, 2000). "We subsequently evaluated whether EGF could reverse the inhibitory effects of SLC5A1 downregulation on colon cancer cell proliferation, invasion, and migration." (PMID 39781340, 2025). "In colon cancer, both Fidarestat and Sorbinil inhibited EGF/FGF-induced growth, migration, and invasion of HT29 and KM20 colon cancer cells, reduced adhesion of tumor cells to growth factor–stimulated endothelial cells and significantly decreased liver metastasis in vivo." (PMID 41154825, 2025). "Induction of homophilic E-cadherin binding in human breast adenocarcinoma MCF-7 and the human colon cancer SW480 cells expressing E-cadherin by incubating cells with recombinant extracellular domain of E-cadherin results in inhibition of EGF-induced DNA synthesis." (PMID 39594667, 2024). "In the literature searches, no information could be obtained regarding the regulation of CAIII in EGF-affected colon cancer." (PMID 39590368, 2024). "For instance, C1GALT1 expression was reported to be required for fibroblast growth factor receptor phosphorylation through O-glycosylation in colon cancer tissue and for binding of epidermal growth factor to its receptor (EGFR) through EGFR O-glycosylation in head and neck cancer." (PMID 38622340, 2024). "Regulation of NRP1 levels in colon cancer cells may involve epidermal growth factor (EGF) and MAPK signaling." (PMID 37894289, 2023). "A study focused on the TME in colon cancer observed that co-culturing macrophages with colon cancer cells stimulated the release of epidermal growth factor (EGF) in CRC cells, which activated the EGFR/PI3K/AKT/mTOR signaling pathways, resulting in a polarization of TAMs into M2 phenotype." (PMID 35912261, 2022). "Consequently, in vitro studies on colon carcinoma cell lines showed that the enzymatic activity of dianthin and the targeting ability of EGF were preserved." (PMID 33924180, 2021). "Taken together, our results demonstrate that fargesin suppressed EGF-induced cell proliferation and cell transformation in premalignant cells and cell proliferation and colony growth of colon cancer cells by modulation of cell cycle regulators via CDK2/cyclin E/p21WAF1/Cip1 complex formation." (PMID 33669811, 2021).
colon carcinoma (continued). "To investigate the effect of VP on human colon cancers, we successfully modeled organoids from patients with colon cancer in a medium supplemented with the growth factors noggin, epidermal growth factor (EGF), human fibroblast growth factor 10 (FGF-10), HEPES, GlutaMAX, Y-27632, and A83-01." (PMID 34055773, 2021). "Taken together, we conclude that fargesin-mediated c-Myc suppression inhibits EGF-induced cell transformation and colon cancer cell colony growth by the suppression of retinoblastoma (Rb)-E2F and CDK/cyclin signaling pathways, which are mainly regulated by MAPK and PKB signaling pathways." (PMID 33669811, 2021). "The fluorescence intensity of the non-pretreated cells incubated with EGF-PLGA@5Fu/PFC NPs was stronger than that of non-targeted NPs (PLGA@5Fu/PFC), and uptake increased in a time-dependent manner, which suggested greater adsorption of EGF-PLGA@5Fu/PFC NPs to colon cancer cells." (PMID 32345258, 2020). "Our results suggested that HOXA5 short RNA, a novel lncRNA, may play a crucial role in colon tumor growth through activation of EGF signaling." (PMID 31159758, 2019). "They showed that EGF 61 G/G genotype was associated with a higher risk of colon cancer, but not rectal cancer." (PMID 31053624, 2019). "However, the present study showed that EGF A61G polymorphism was a risk factor for CRC, but not only for colon cancer." (PMID 31053624, 2019). "Solic and colleagues first found that colon cancer cells could undergo EMT when treated with EGF in 1995." (PMID 30348114, 2018). "Our data showed that ERRα played a central role in the EGF-mediated growth of colon cancer cells; thus, we hypothesized that inhibiting ERRα may increase the sensitivity of colon cancer cells to trametinib." (PMID 30185207, 2018). "Furthermore, we found that trametinib partially restrained the up-regulation of ERRα induced by EGF exposure, and the inhibition of ERRα increased the sensitivity of colon cancer cells to trametinib." (PMID 30185207, 2018). "EGF concentrations and treatment times were based on previous studies with colon cancer cell lines." (PMID 29515334, 2018). "Integrin β1 localization is regulated by the guanosine-5′-triphosphate hydrolase Rab25 and integrin β1 levels are elevated in the serum of colon cancer patients; thus, the present study examined the effects of epidermal growth factor (EGF) and Rab25 on integrin β1 localization in colon cancer cells." (PMID 29515334, 2018). "Furthermore, our study first found that the suppression of ERRα completely reduced the survival of EGF-treated colon cancer cells, though it has been known for many years that ERRα expression is regulated, in part, via the EGF signalling pathway." (PMID 30185207, 2018). "We therefore investigated whether B4GALNT3 could regulate stem-like potential of colon cancer cells via the EGF/EGFR pathway." (PMID 25003232, 2014). "A previous report demonstrated that EGF induced colon cancer proliferation." (PMID 25122478, 2014). "However, little information is available about the role of NADPH oxidase in regulating NF-κB activation and HO-1 expression following EGF stimulation in human colon cancer cells." (PMID 25122478, 2014). "Next, to examine whether HO-1 mediates EGF-induced colon cancer cell proliferation, a HO-1 inhibitor (snPP) was used." (PMID 25122478, 2014). "Furthermore, EGF-induced colon cancer cell proliferation was inhibited by Sn(IV)protoporphyrin-IX (snPP, an HO-1 inhibitor)." (PMID 25122478, 2014). "Several studies demonstrated that EGF plays an important role in the development of colon cancer." (PMID 25122478, 2014). "The importance of EGF in the development of colon cancer was emphasized in recent years." (PMID 25122478, 2014). "However, colon cancer cells also grew as flat, disc-like colonies when cultured with EGF plus Wnt, R-Spondin1 and Noggin." (PMID 23638973, 2013). "When colon cancer cells were cultured in 3-D with EGF, they grew as round spheroid colonies." (PMID 23638973, 2013).
colon carcinoma (continued). "The adhesion of CC531, Caco2 and HT29 colon carcinoma cell lines to an autologous monolayer of rat mesothelial cells pre-incubated with factors released after surgical trauma (IL-1β and EGF) resulted in at least 60% more cell adhesion in a dose-dependent manner." (PMID 22296757, 2012). "Both HCT116 and HT29 colon cancer cells grew in large round, unattached floating spheroid colonies (termed colonospheres) when they were cultured in serum free medium supplemented with 1×B27, 20 ng/ml EGF, 10 ng/ml bFGF." (PMID 22745705, 2012). "EGF-induced proliferation of HT-29 cells was inhibited by genistein, suggesting that genistein may affect the EGF pathway in colon cancer cells." (PMID 21639915, 2011). "EGF promotes proliferation and is known to be critical to the progression of colon cancer." (PMID 21639915, 2011). "Epidermal growth factor (EGF) was used to stimulate colon cancer caco-2 cells." (PMID 23554613, 2010). "Our study demonstrated that stimulation by EGF enhanced the chemosensitivity of caco-2 cells to 5-FU, which may be a novel therapeutic protocol in colon cancer." (PMID 23554613, 2010). "In addition, colon cancer spheres require ultra-low-attachment conditions, epidermal growth factor and fibroblast growth factor-2, plus culture for 4 weeks, whereas colospheres form in 1 day, without adding exogenous growth factors." (PMID 19603013, 2009). "The aims of this study were to characterize the endogenous epidermal growth factor (EGF)-like ligands expressed in two polarizing colon cancer cell lines, HCA-7 Colony 29 (HCA-7) and Caco-2, and to examine the effects of cell polarity on EGF receptor-mediated mitogenesis." (PMID 10362109, 1999). "Thus, we revealed novel crosstalk between the VEGF and the EGF pathways in colon cancer cells." (PMID 31717527, 2019). "Therefore, it is possible that PKM2 could play a role in β-catenin nuclear localization driven by EGF signaling in colon cancers where this pathway is hyperactive." (PMID 29214019, 2017). "In addition, EGF may also regulate the expression functions of claudins in ovarian and colon cancer cells during cancer development via the EGF-activated ERK1/2 and PI3K-Akt pathways." (PMID 28160565, 2017). "TOPK could promote EGF-induced cell transformation and colon cancer development." (PMID 27016416, 2016). "Moreover, EGF induced an increase in c-Src phosphorylation at Tyr416 in human colon cancer cells." (PMID 25122478, 2014). "Moreover, HO-1 is involved in EGF-induced colon cancer cell proliferation." (PMID 25122478, 2014). "Moreover, HO-1 mediates EGF-induced colon cancer cell proliferation." (PMID 25122478, 2014). "Moreover, induction of HO-1 expression mediates EGF-induced colon cancer cell proliferation." (PMID 25122478, 2014). "Moreover, overexpression of HO-1 mediates EGF-induced colon cancer cell proliferation." (PMID 25122478, 2014). "In colon cancer cell lines (HT29 and KM20), stimulation with growth factors such as EGF and FGF increased cancer cell proliferation, migration, invasion, and adhesion to endothelial cells." (PMID 41154825, 2025). "After adding hesperidin and EGF to colon cancer cells, the EGFR phosphorylation levels were more increased than those of colon cancer cells treated solely with Hesperidin, while the protein level of EGFR remained unchanged." (PMID 39781340, 2025).